FER1L6-AS1 (FER1L6 antisense RNA 1)
Synonyms: C8orf54; FLJ35721
Gene: Long non-coding RNA gene on chromosome 8 (123,984,138 to 124,040,782, reverse strand). Ensembl gene ENSG00000181171.
Diseases named in the same sentence as FER1L6-AS1 in open-access papers:
FER1L6-AS1 is named in the same sentence as 1 disease in open-access papers, as found by Europe PMC text mining. Sharing a sentence is not in itself a finding about the gene and the disease. The quoted sentences say what the papers report.
esophageal squamous cell carcinoma (1 paper, 2019). Esophageal squamous cell carcinoma (ESCC) is a type of esophageal carcinoma (EC) that can affect any part of the esophagus, but is usually located in the upper or middle third. "The fifth most DM ncRNA was the FER1L6 antisense RNA 1 (FER1L6-AS1) gene, which was found to be dysregulated in esophageal squamous cell carcinoma." (PMID 31892232, 2019).